SETD2 (SET domain containing 2, histone lysine methyltransferase)
Diseases named in the same sentence as SETD2 in open-access papers (continued):
Sharing a sentence is not in itself a finding about the gene and the disease.
leukemia (continued). "Given the gene reversal preferences, all these inhibitors were selected as potential therapeutics for further validation in SETD2-mutant leukemia." (PMID 40300107, 2025). "Together, these findings support the conclusion that the MYC signature, a subset of the SETD2 LOF leukemia transcriptomic signatures, is a critical indicator of the actual efficacy of the predicted drug candidates." (PMID 40300107, 2025). "Collectively, our study identifies G9a inhibitors as a promising therapeutic avenue for SETD2-mutant leukemia and provides novel insights into refining drug prediction strategies." (PMID 40300107, 2025). "In this study, we integrated computational prediction with epigenetic compound library screening to systematically identify potential therapeutic agents for SETD2-mutant leukemia." (PMID 40300107, 2025). "Mechanistically, G9a-i likely reduce H3K9me2 levels at the MIR100HG locus, specifically upregulating the embedded miRNA let-7a-2 to suppress the MYC pathway, which is crucial for the survival of SETD2-mutant leukemia." (PMID 40300107, 2025). "SETD2-mutant leukemia is known for its aggressiveness and chemo-resistance, yet effective therapeutic options remain limited." (PMID 40300107, 2025). "In CML cell lines, SETD2 knockout-induced overexpression resulted in imatinib insensitivity and enrichment of leukemia stem cells." (PMID 37359376, 2023). "The low expression of SETD2 leads to proliferative advantage, increased colony formation and accelerated leukemia development of fusion-protein expressing cancer cells in MLL." (PMID 32859239, 2020). "There are at least two possible explanations to link SETD2 inactivation to the survival of leukemia cell." (PMID 30922329, 2019). "Conversely, several genome-scale CRISPR (Clustered Regularly Interspaced Short Palindromic Repeats)/Cas9 screens identified SETD2 as an essential gene in leukemia cells, proposing alternative functions of SETD2 in addition to its tumor suppressor role." (PMID 30818762, 2019). "In contrast, other studies indicate that SETD2 is critically required for the proliferation of leukemia cells." (PMID 30818762, 2019). "In the following, we will highlight the most important cellular functions of SETD2 and their potential links to leukemia." (PMID 30818762, 2019). "In MLL-fusion expressing leukemia, a combinatorial effect of SETD2 downregulation and pharmacological inhibition of DOT1L was observed." (PMID 30818762, 2019). "All our data show a strong functional requirement for the expression and activity of SETD2 in the progression of MLL-leukemia." (PMID 29777171, 2018). "Here, the authors describe a dependency of MLL-leukemia cells on the methyltransferase SETD2 to maintain genomic integrity during leukemia initiation and maintenance." (PMID 29777171, 2018). "As it is possible that alternative molecular mechanisms pertain during initiation of MLL-rearranged leukemia, we tested the involvement of SETD2 in this process." (PMID 29777171, 2018). "Functional investigation of 128 conserved MLL-fusion-interactors identifies a specific role for the lysine methyltransferase SETD2 in MLL-leukemia." (PMID 29777171, 2018). "Based on these findings, we hypothesized that this approach could be applied to identify potential drugs for SETD2-mutant leukemia." (PMID 40300107, 2025). "Previously, we identified SETD2 LOF mutations in approximately 6% of acute myeloid leukemia (AML) and acute lymphoid leukemia (ALL), with a particularly high prevalence of over 20% in mixed lineage leukemia-rearranged (MLL-r) leukemia." (PMID 40300107, 2025). "Moreover, considering the limited variety of epigenetic drugs in the database and potential crosstalk among H3K36me3 and other epigenetic modifications, additional exploration of these drugs in SETD2-mutant leukemia is warranted." (PMID 40300107, 2025). "Consequently, there is an urgent need to explore alternative therapeutic strategies for SETD2-mutant leukemia." (PMID 40300107, 2025).
leukemia (continued). "This supports their established efficacy against MLL-r leukemia and indicates that SETD2 mutation does not affect their potency." (PMID 40300107, 2025). "Our aim was to identify inhibitors that exhibit hypersensitivity in SETD2-mutant leukemia." (PMID 40300107, 2025). "Hence, the overexpression of SETD2 has been postulated to develop chemotherapy resistance in many cancers, including leukemias." (PMID 38328782, 2024). "Finally, we summarize the progress of several epigenetic drugs targeting SETD2/H3K36me3, including leukemia and lung cancer." (PMID 37359376, 2023). "Histone deacetylase (HDAC)-inhibitor drugs could be considered for treatment in the clinical scenario of upregulated MITF and SETD2 inhibitors are currently being investigated in the treatment of leukemia." (PMID 31712784, 2019). "Another study found that loss of SETD2 led to down-regulated expression of the tumor suppressor ASXL1 (Additional Sex Combs-Like protein 1) and an upregulation of ERG, resulting in accelerated leukemia development." (PMID 30818762, 2019). "The availability of specific small-molecule inhibitors of SETD2 function together with combinatorial approaches might represent a therapeutic strategy for patients suffering from leukemia and other SETD2-dependent malignancies." (PMID 30818762, 2019). "Thus, although studies of SETD2-dependent processes in cancer have contributed to a better understanding of the SETD2–H3K36me3 axis, many open questions remain regarding its specific role in leukemia." (PMID 30818762, 2019). "shRNA-mediated knockdown of SETD2 led to proliferative advantage, increased colony formation and accelerated leukemia development of fusion-protein expressing leukemia cells in vitro and in vivo, further establishing a tumor suppressive role of SETD2 in leukemia." (PMID 30818762, 2019). "However, the functional significance of SETD2 inactivation is best described in renal cell carcinoma and leukemias in people where it has a tumor suppressor function." (PMID 31341965, 2019). "Finally, a recent report showed that while homozygous Setd2 deletion in the mouse strongly delayed leukemogenesis, heterozygous Setd2 deletion accelerated MLL-AF9-induced leukemia and caused chemoresistance." (PMID 29777171, 2018). "Finally, we aimed to obtain insight into the molecular mechanism that functionally connects SETD2 activity with MLL-fusion-induced leukemia." (PMID 29777171, 2018). "Our studies provide novel insights into the biology of MLL-fusion proteins and identify an unexpected dependency of MLL-fusion-expressing leukemia cells on the methyltransferase SETD2 during leukemia initiation and maintenance, validating SETD2 as an actionable target MLL-rearranged leukemia." (PMID 29777171, 2018). "However, it remains unclear whether these modifications are elevated in SETD2-mutant leukemia and whether they represent potential therapeutic targets." (PMID 40300107, 2025). "Downregulation of the SETD2 gene encoding a histone H3K36 methyltransferase resulted in a global loss of H3K36 tri-methylation and contributed to both initiation and progression during leukemia development by promoting the self-renewal potential of leukemia stem cells." (PMID 34209866, 2021). "We investigated the effect of the more potent chemotype (SX045) against SETD2 in a cell-based assay using MOLM-13 and MV4-11 leukemia cells, which were shown before to be particularly sensitive to SETD2 perturbation." (PMID 34045440, 2021). "Using a domain-focused CRISPR/Cas9 mutagenesis approach, it was shown that the catalytic activity of SETD2 was essential, as mutagenesis of the SETD2 SET domain impaired the proliferation of MLL-AF9-expressing leukemia cells." (PMID 30818762, 2019). "As our screening data indicate that SETD2 knockdown selectively inhibits the proliferation of MLL-fusion-expressing cells, we sought to extend this observation to a larger panel of human leukemia cell lines." (PMID 29777171, 2018).
leukemia (continued). "In summary, we describe a novel dependency for SETD2 in the initiation and maintenance of MLL-rearranged leukemia, highlighting a novel vulnerability in this disease." (PMID 29777171, 2018). "Previous study has shown that SETD2-mutant leukemia exhibits reduced phosphorylated ATR, indicating impaired DDR; however, the efficacy of ATM/ATR-i in SETD2-mutant leukemia remains unknown." (PMID 40300107, 2025). "To date, however, the involvement of alternative splicing to leukemia development in the context of SETD2 has not been documented." (PMID 30818762, 2019). "While most leukemia cells isolated from moribund recipients of control AML cells showed robust shRNA expression (as measured by GFP levels), shRNA-expressing cells were strongly outcompeted by shRNA-negative cells in case of Setd2 knockdown in vivo." (PMID 29777171, 2018). "Inactivating lesions in SETD2 have been recently implicated in 22.2% of MLL gene-rearranged leukemia pathogenesis and also in 4.6% of patients with leukemia that did not have MLL rearrangements." (PMID 26527318, 2016). "Furthermore, H3K36me3, mediated by SETD2, interacts with H3K27me3 and DNMTs; however, our results indicate that these interactions do not play a specific role in inhibiting SETD2-mutant leukemia." (PMID 40300107, 2025). "Notably, with NSD1, and ASH1L, two other H3K36 methyltransferases, SETD2 were demonstrated as a critical gene in the development of castration-resistant prostate cancer (CRPC), similar to MLL complex family members for leukemia." (PMID 39591760, 2025). "Given the dependence of the dual H3K36me3-H3K79me2 signature across MLL-target genes on SETD2 and the strong requirement of MLL-leukemia for the H3K79 methyltransferase DOT1L21, we reasoned that SETD2 loss might cooperate with pharmacologic inhibition of DOT1L." (PMID 29777171, 2018).
breast carcinoma (32 papers, 2009 to 2025). "SETD2 has been described to be mutated in all subtypes of breast cancer up to 2.62 %, and notably SETD2 mutation incidence in triple-negative breast cancer is 1.2 %." (PMID 39591760, 2025). "SETD2 mutations have been correlated with shorter progression-free and overall survivals in metastatic renal cell carcinoma and breast cancers." (PMID 34925233, 2021). "According to the TCGA and METABRIC databases, SETD2 is mutated in all subtypes of breast cancer with a proportion of 2.62%, and its incidence in triple-negative breast cancer is 1.2%." (PMID 32231741, 2020). "The discovery of SETD2 as a frequently mutated gene in phyllodes tumors of the breast (PT) suggests SETD2 may serve as a biomarker for this aggressive breast cancer subtype." (PMID 40565165, 2025). "According to TCGA and METABRIC databases, SETD2 is mutated in 2.62% of all BC subtypes and 1.2% of triple-negative breast cancer cases." (PMID 37359376, 2023). "Further studies have shown that in all types of breast cancer, the expression level of SETD2 is significantly related to the prognosis of patients and that the higher the expression, the better the prognosis." (PMID 32231741, 2020). "Consistent with our findings, lower SETD2 mRNA levels have been reported in breast cancer tissues, thereby linking decreased SETD2 mRNA levels to tumorigenesis." (PMID 32392781, 2020). "We next performed real-time qPCR on the breast cancer cell lines and normal breast tissues using primer sequences specific to the candidate genes SETD2, BAP1 PBRM1 and PARP-3 (Figure 2Ci-2Civ)." (PMID 28977912, 2017). "Gene copy number variation (CNV) analysis of SETD2, BAP1, PARP-3 and PBRM1 within a panel of nine breast cancer cell lines demonstrated single copy number loss of all candidate genes within five (56%) cell lines (including 21NT cells)." (PMID 28977912, 2017). "SETD2 is the only mammalian histone H3K36 trimethyltransferase that has been suggested to display tumor suppressor activity in breast cancer and renal cell carcinoma." (PMID 26527318, 2016). "We found that for seven HMTs (KMT2C, SETDB2, SETD2, SETMAR, PRDM1, PRDM5, and PRDM8), copy number amp/gain or deletion was significantly associated (p<0.05) with shorter survival in breast cancer patients." (PMID 25537518, 2015). "SETD2 expression levels were significantly lower in samples from patients who developed metastasis, local recurrence, or died of breast cancer when compared to those who were disease free for > 10 years (p = 0.041)." (PMID 19698110, 2009). "This is the first study in the literature to examine the direct relationship between SETD2 mRNA expression and breast cancer." (PMID 19698110, 2009). "The strength of our report lies in the use of robust RT-PCR methodology to analyze SETD2 mRNA expression in a cohort of breast cancer patients with a long-term follow up." (PMID 19698110, 2009). "Further research is required to confirm the role of SETD2 gene in the pathogenesis of breast cancer including immunohistochemistry studies, in vitro experiments and the preparation of animal models with suppressed SETD2 gene." (PMID 19698110, 2009). "This is the first study in the literature to examine the direct relationship between SETD2 and breast cancer." (PMID 19698110, 2009). "We are the first group to investigate SETD2 expression in human breast cancer and identify a possible TSG function." (PMID 19698110, 2009). "More recently, circular RNA circ_SETD2, produced by reverse splicing of SETD2 gene, has been shown to repress breast cancer progression through the regulation of SCUBE2 (signal peptide-CUB-epidermal growth factor-like domain-containing 2) via competitively binding to miR-155-5p." (PMID 39591760, 2025).
breast carcinoma (continued). "Alterations of the histone methyltransferase SETD2 are also correlated with prognosis in renal cell cancer and may be involved in resistance to chemotherapy in breast cancer, as was observed with paclitaxel in our study." (PMID 35122700, 2022). "SETD2 mutations are associated with shorter PFS and OS in metastatic RCC and breast cancer." (PMID 35686121, 2022). "In the present study, overexpression of BAP1, but not PARP3, PBRM1 or SETD2, was associated with significant (but not complete) repression of hTERT transcription within 21NT breast cancer cells." (PMID 28977912, 2017). "Mapping of chromosome 3 structure in a single hTERT-repressed 21NT-#3fragment hybrid clone, revealed a 490kb region of deletion localised to 3p21.3 and encompassing the histone H3, lysine 36 (H3K36) trimethyltransferase enzyme SETD2; a putative tumour suppressor gene in breast cancer." (PMID 28977912, 2017). "SETD2 alterations were found in 1% of breast cancer (n=482)." (PMID 25611383, 2015). "Our objective was to determine, using quantitative PCR, whether the mRNA expression levels of SETD2 were consistent with a tumour suppressive function in breast cancer." (PMID 19698110, 2009). "SETD2 was found to be expressed in both benign and breast cancer specimens." (PMID 19698110, 2009). "The aim of our study was to determine, using quantitative PCR, whether the mRNA expression levels of SETD2 were consistent with a tumour suppressive function in human breast cancer." (PMID 19698110, 2009). "Taken together, these results indicated that SETD5 may be an oncogenic factor; this finding is supported by the oncogenic role of other SET domain protein family members, except SETD2, which was demonstrated to be a tumor suppressor in renal and breast carcinomas." (PMID 31345185, 2019). "Previous reports have indicated that the SETD2 gene may play a tumor suppressor role in some types of cancer; for example, it was reported that a lower transcript level of SETD2 was found in breast cancer tissues and that the development of the tumor was correlated with reduced SETD2 mRNA levels." (PMID 25714014, 2015). "In the CBD signaling, the key axis was formed by SUPT16H, SETD2, and H2BC12, which suggests epigenetic regulation by CBD in the restoration of an epithelial phenotype of breast cancer cells, providing new targets for anticancer therapy." (PMID 40429863, 2025). "Circ_SETD2 binds competitively to miR-155-5p and upregulates SCUBE2 expression, thereby inhibiting breast-cancer progression." (PMID 36142489, 2022). "The overexpression of circ_SETD2 and SCUBE2 increases cell-cycle arrest, induces apoptosis, and inhibits cell proliferation, migration, and invasion in breast-cancer cells." (PMID 36142489, 2022). "We identified a 490kb region, localised to 3p21.3, which encompasses the putative breast cancer tumour suppressor gene and H3K36 trimethyltransferase known as SETD2." (PMID 28977912, 2017). "In addition, we have demonstrated that SETD2, BAP1, PBRM1 and PARP-3 are all down-regulated in the breast cancer cell line 21NT when compared to normal cells (HMEC), making them prime targets for tumour suppression / telomerase repression in breast cancer." (PMID 28977912, 2017). "Due to the high frequency of gene copy number loss within breast cancer cells, our results provide additional evidence that SETD2, BAP1, PBRM1 and PARP-3 may function as tumour suppressors in breast cancer cells." (PMID 28977912, 2017).
breast carcinoma (continued). "In order to investigate the functional role of SETD2, BAP1, PBRM1 and PARP-3 in regulating hTERT transcription, we examined the effect of forced, stable overexpression of candidate genes on pre-spliced hTERT expression within 21NT breast cancer cells." (PMID 28977912, 2017). "Similarly, SETD2 mRNA levels have been found to be significantly lower within tumour samples than matched adjacent non-cancerous tissue (ANCT) samples from 25 breast cancer patients." (PMID 28977912, 2017).